HLA-C (major histocompatibility complex, class I, C)
Diseases named in the same sentence as HLA-C in open-access papers (continued):
Sharing a sentence is not in itself a finding about the gene and the disease.
COVID-19 (continued). "Here authors identify an HLA-C-restricted conserved immunodominant SARS-CoV-2 nucleocapsid epitope in COVID-19 convalescent donors from early waves of the pandemic and provide structural bases for its recognition by the T cell receptor." (PMID 40877317, 2025). "For example, the HLA-A*11:01 and HLA-C*04:01 alleles have been linked to severe disease, whereas the HLA-DRB1*04:01 allele has been associated with protection against severe COVID-19." (PMID 40650195, 2025). "HLA allele data from the NGS of 332 individuals from the Shenzhen Third Peoples’ Hospital, China revealed that HLA-C*14:02 was significantly prominent in severe compared to mild COVID-19 cases (p = 0.003)." (PMID 38667755, 2024). "The comprehensive effect of HLA-C*04:01 on severe COVID-19 was depicted by the odds ratio of 1.1 (p-value = 5.8 × 10−4)." (PMID 38667755, 2024). "In this study, they genotyped HLA-C in 72 COVID-19-infected individuals and 3886 healthy individuals." (PMID 38667755, 2024). "A study with Chinese individuals showed that HLA-C*14:02 significantly correlated with severe COVID-19." (PMID 38667755, 2024). "In this study, we investigated the effect of HLA-B and HLA-C mRNA expression levels on COVID-19 severity in positive COVID-19 individuals." (PMID 38674456, 2024). "High binding affinity was observed between epitopes of SARS-CoV-2 and HLA-C*12:02, which suggests a high immune response against COVID-19." (PMID 38667755, 2024). "HLA-C*08:02, HLA-C*12:03, and HLA-C*16:01 were more prevalent in mild COVID-19 than severe COVID-19 (p = 0.0014) in a Spanish Mediterranean Caucasian population." (PMID 38667755, 2024). "In addition, HLA-C*04:01 could be related to COVID-19 susceptibility." (PMID 38667755, 2024). "There was a chance that the correlation between COVID-19 severity and HLA-C*04:01 was a statistical artifact in one of their datasets." (PMID 38667755, 2024). "Co-localization analysis identified LZTFL1, MUC4, OAS1, HLA-C, SLC22A31, FDX2, and MAPT as genes involved in COVID-19-mediated causation of MM." (PMID 38400850, 2024). "The involvement of inflammation, HLA-C*04, and HLA-B*35 in COVID-19 severity highlights the potential roles of both the adaptive and innate immune responses against SARS-CoV-2." (PMID 37708194, 2023). "data, regarding two hypomethylated CpG loci, associated with the clinical severity of COVID-19, in an S-shore region of a CGI encompassing the first exons of HLA-C gene." (PMID 36325330, 2022). "HLA-C expression significantly decreases in COVID-19 patients, especially in those with a more severe prognosis and without other possibly confounding co-morbidities." (PMID 36325330, 2022). "The frequency of HLA-C*08:02 was significantly higher in individuals of our cohort with mild COVID-19 (18.8%) in comparison with individuals with critical COVID-19 (1.6%; p = 0.0024; pc = 0.0240)." (PMID 35960731, 2022). "Pairing analysis of the frequencies of KIR2DL2/2DL3/2DS2 and HLA-C in COVID-19 patients and healthy persons." (PMID 35874712, 2022). "In the case of SARS-CoV-2 infection, HLA-A*11, HLA-C*01, and HLA-DQB1*04 are associated with mortality by COVID-19, whereas another HLA, such as HLA-A:02:01, is implicated in the activation of T cells." (PMID 35062298, 2022). "Transcript expression of HLA-C was evaluated in 61 COVID-19 patients, eight post-COVID-19 subjects and eight controls with no previous infection of SARS-CoV-2." (PMID 36325330, 2022). "This study assessed the frequency of the KIR and HLA-C genes in COVID-19 patients infected in the early phase of the pandemic and healthy people living in Wuhan, China, and identified specific protective or susceptible KIR/HLA-C gene pairings." (PMID 35874712, 2022). "Regarding COVID-19 severity, the HLA-A*33, ACE1 Ins, and TMPRSS2 rs12329760T alleles were associated with protection against severe forms, while the HLA-B*38, HLA-C*6, and ApoE rs429358C alleles were associated with risk for severe forms of COVID-19." (PMID 35793369, 2022).
COVID-19 (continued). "Of note, it has been shown that ciliated cells from severe COVID-19 patients display a reduced overexpression of HLA-C, among other genes, compared with those from patients with moderate symptoms." (PMID 36325330, 2022). "The regional distribution of HLA-C*07 in the Italian population is positively correlated with COVID-19 morbidity and mortality." (PMID 35874712, 2022). "Overall, both symptomatic and asymptomatic COVID-19 patients showed lower HLA-C expression than controls (p-value < 0.0001)." (PMID 36325330, 2022). "In patients with mild/moderate to severe COVID-19, due to high prevalence of HLA-C*04:01, these effects provide a decrease of the HLA class I loci heterozygosity and a down-modulation of the predicted HLA class I ability to recognize SARS-CoV-2 peptides." (PMID 35185875, 2022). "Further analyses will be necessary to determine the actual role of HLA-C locus as a predictive biomarker for COVID-19 progression." (PMID 35960731, 2022). "In a Chinese study, HLA-B*15:27 and HLA-C*07:29 were more frequent in COVID-19 patients vs. control subjects, with the results staying significant after correction." (PMID 33807915, 2021). "HLA-A, HLA-B, and HLA-C genotypes of n = 111 deceased patients with COVID-19 (Moscow, Russia) and n = 428 volunteers were identified with next-generation sequencing." (PMID 33732261, 2021). "While our results suggest the presence of a correlation between HLA-C*05 and death due to COVID-19, prospective genetic studies will be required to study causal relationships." (PMID 33233780, 2020). "The data suggest that, in addition to HLA-A and HLA-B-restricted T cells, HLA-C-restricted T cells may play an important role in controlling COVID-19." (PMID 40877317, 2025). "In Europeans, HLA-C*04:01 has been shown to influence severe COVID-19." (PMID 38667755, 2024). "Our results highlight an association between HLA-C-mediated viral peptide binding and effective immune responses to SARS-CoV-2 infection that suggests potential avenues for further research into the immunologic mechanisms underlying severe COVID-19." (PMID 39337964, 2024). "HLA-C*04:01 was higher in COVID-19-infected individuals than in healthy individuals." (PMID 38667755, 2024). "Except for HLA-C*04:01, none of the alleles found to be associated with the severe course of COVID-19 in Asians were confirmed in our study." (PMID 39768617, 2024). "Additional studies are imperative to understand the role of HLA-C*05 in COVID-19." (PMID 38667755, 2024). "Furthermore, KIR2DS4 polymorphisms and HLA-C*04:01 increased the SARS-CoV-2 viral quantity and led to severe COVID-19 in individuals co-infected with HIV." (PMID 38667755, 2024). "The late immune response triggered by low HLA binding affinity may be the reason for the severe COVID-19 in individuals with HLA-C*04:01." (PMID 38667755, 2024). "Unsurprisingly, the “near to epithelial cell” myeloid population shows higher COVID-19 signatures score and highly expresses multiple MHC Class I and II related genes, such as B2M, HLA-A, HLA-B, HLA-C, HLA-E, and HLA-DRA, which are associated with the interferon (IFN) response." (PMID 37120608, 2023). "In conclusion, our results pointed out the reduction of HLA-C expression in COVID-19 patients, more pronounced in the severe cases, suggesting this molecule involved in antigen presentation as a potential prognostic marker and therapeutic target in RNA virus infections." (PMID 36325330, 2022). "Interestingly this last-mentioned CGI (chr6:31276241-31276526), upstream HLA-C, was hypermethylated in COVID-19 patients compared to controls." (PMID 36325330, 2022). "Other HLA-C alleles from group HLA-C1 have been described to show a higher degree of recognition of SARS-CoV-2 peptides, and HLA-C*01 has also been correlated with a higher mortality during COVID-19 in the Spanish population." (PMID 35960731, 2022).
COVID-19 (continued). "A series of genetic studies with a Sardinian/Italian sample potentially support this hypothesis, by reporting a significantly high prevalence of both, HLA-C*04:01 allele and NK-cell inhibitor KIR2DL1 receptor, in COVID-19 cases." (PMID 35185875, 2022). "Another study indicates HLA-C*04:01 association with susceptibility but not COVID-19 severity in the Sardinian/Italian population." (PMID 35185875, 2022). "In comparison with controls, a non-significant difference in HLA-C*04:01 allele frequency was observed for the COVID-19 patients with mild/moderate (P=0.93) and severe (P=0.15) symptoms composing the group of hospitalized inpatients." (PMID 35185875, 2022). "This is the case of C1 alleles such as HLA-C*08 and-C*12, which have also been related to a better cytotoxic response against SARS-CoV-2 and, accordingly, the presence of HLA-C*08:02 and -C*12:03 was significantly higher in individuals with mild COVID-19 from our cohort." (PMID 35960731, 2022). "HLA-C*04:01 exerted a sex-dependent differential distribution between subgroups of COVID-19 cases." (PMID 35185875, 2022). "However, the presence of HLA-C*08:02 was significantly higher in individuals with mild COVID-19 (18.8%) in comparison with individuals with critical COVID-19 (1.6%; p = 0.0024; pc = 0.0240)." (PMID 35960731, 2022). "In addition, the size of our cohort is similar to other studies previously published that also validate a correlation between HLA-C and an increased COVID-19 severity in the Spanish population." (PMID 35960731, 2022). "Correlation analysis of KIR/HLA-C between mild and severe COVID-19 patients." (PMID 35874712, 2022). "Determination of HLA genetic polymorphisms showed that the alleles HLA-A*11, HLA-C*01, and HLA-DQB1*04 could be associated with mortality at 30 days for patients with COVID-19." (PMID 35062298, 2022). "Interestingly, our study of adult COVID-19 cases identified that an epigenetic mark in HLA-C (major histocompatibility complex, class I, C) was associated with the severe disease." (PMID 35770252, 2022). "The exact role of HLA-C*04:01 to the COVID-19 severity merits further study." (PMID 35185875, 2022). "Thus, the results of our study strongly suggest a putative role of HLA-C genetic variation in the development of a specific immune response to COVID-19." (PMID 35185875, 2022). "In addition, HLA-C*04:01 was also observed to be in association with poor viral control of HIV and severe clinical course of COVID-19." (PMID 35602060, 2022). "Although HLA-C, had the greatest antigenic peptide capacity from SARS-CoV-2, HLA-B and HLA-A, could be more relevant based on COVID-19 risk of infection in LATAM countries." (PMID 34205992, 2021). "We expect that HLA-A*11:01 and HLA-C*12:02-HLA-B*52:01 could potentially act as a predictive marker for the severity of COVID-19 in the Asia region." (PMID 33968060, 2021). "This is especially evident for COVID-19 patients with HLA-C*04:01, in whom disease prognosis measured by mechanical ventilation-free days was statistically significant after Bonferroni’s correction and may hold potential clinical value." (PMID 34344463, 2021). "This suggests that HLA-B mRNA expression levels are associated with increased disease severity, while HLA-C expression might not play a significant role in COVID-19 disease severity." (PMID 38674456, 2024). "We also investigated whether HLA-C expression could be correlated with COVID-19 severity." (PMID 36325330, 2022). "Additionally, a study of HLA frequencies distributed in 82 Chinese patients, with mild or severe but not critical disease, revealed a significant increase in HLA-C*07:29 and -B*15:27 alleles in COVID-19 patients." (PMID 34685388, 2021). "Among them, HLA-C, TCF19, and ADAM15 were shared by PrCa and the two COVID-19 severity phenotypes, while CCHCR1 was shared by PrCa and all three COVID-19 phenotypes." (PMID 41210689, 2025).
COVID-19 (continued). "Our study did not confirm these findings, as we observed decreased frequencies of HLA-C*07:04 and DQB1*03:03 in COVID-19 patients." (PMID 39768617, 2024). "This study identifies a link between HLA-C peptide binding repertoires and the severity of SARS-CoV-2 infections observed at Michigan Medicine in the early stages of the COVID-19 pandemic." (PMID 39337964, 2024). "Besides, due to relatively low frequency than HLA-C*04:01, and non-significant association with COVID-19 (P>0.36), it does not preclude a significant association between a scanty HLA class I heterozygosity and COVID-19 (after controlling for HLA-C*07:01, P<0.035)." (PMID 35185875, 2022). "DNA of blood samples from 257 COVID-19 patients were extracted and used to detect KIR and HLA-C gene frequencies using single strain sequence-specific primer (SSP) PCR." (PMID 35874712, 2022). "Thus, patients with a HLA-C*05 and KIR2DS4fl pair, which is most frequently seen in high mortality countries, may be prone to an excess cytokine response and suffer from hypercytokinemia, characteristic of elderly patients with severe COVID-19." (PMID 33233780, 2020). "Furthermore, NK cells from COVID-19 patients over-express inhibitory KIR2DL1 or KIR2DL2/DL3 receptors, which specifically recognize HLA-C molecules, compared to healthy donors." (PMID 37342247, 2023). "Our data implied that KIR/HLA-C is not related to the progression of COVID-19." (PMID 35874712, 2022). "However, in this study HLA-C*07:29 was found in one COVID-19 patient only, but in no individuals in the control group." (PMID 34344463, 2021). "In these analyses, certain research could not find a correlation between HLA-C*04:01 and COVID-19." (PMID 38667755, 2024).
schizophrenia (60 papers, 2012 to 2025). A major psychotic disorder characterized by abnormalities in the perception or expression of reality. "HLA-C*01:02 was positively associated with schizophrenia, while HLA-C*07:01 was negatively associated with schizophrenia." (PMID 34805976, 2021). "The GWAS studies to date have not found the gene(s) responsible or causative variants in the MHC locus, although the HLA-B and HLA-DRB1 loci were protective, and the HLA-C increased risk for schizophrenia." (PMID 26998349, 2016). "HLA-C is a risk factor for schizophrenia that is interferon-inducible." (PMID 34954808, 2022). "HLA-C has been shown to be strongly associated with schizophrenia by multiple past studies." (PMID 34805976, 2021). "Only HLA-C and FLOT1 are inferred to have direct causal effects on schizophrenia risk, and all other 15 peripheral genes (OR2J3 excluded) may have causal effects on schizophrenia that only are mediated by FLOT1 and/or HLA-C expression." (PMID 40270926, 2025). "The interaction among HLA-C, HLA-DRB1, and HLA-DQB1 is likely to take part in schizophrenia’s pathogenesis as well." (PMID 34805976, 2021). "From the pathway enrichment analysis, subnetwork 26 was enriched with proteins involved in an antigen processing and presentation pathway that consisted of three PCOSrps (HLA-A, HLA-C, and HLA-E) shared between PCOS and schizophrenia." (PMID 31216618, 2019). "HLA class I genes such as HLA-A, HLA-B and HLA-C are located in the MHC region and are included in the schizophrenia specific module, S_R_only_M1, from our replication study." (PMID 27898074, 2016). "Regarding the HLA system, studies to date have reported negative correlations between HLA-C*07 and schizophrenia and positive correlations between HLA-B*58:01, C*07:01, DQA1*01:01, DQB1*05:01, and DPB1*17:01 and posttraumatic stress disorders." (PMID 36231907, 2022). "No studies have been conducted on specific mechanisms of HLA-C, HLA-DRB1, and HLA-DQB1’s interventions in schizophrenia pathogenesis, but their interaction is much likely to contribute to the disease." (PMID 34805976, 2021).
type 1 diabetes (45 papers, 2007 to 2025). "Association of the HLA class I region, independent of known HLA class II effects, has now been detected for several AIDs, including strong association of HLA-B with type 1 diabetes and HLA-C with multiple sclerosis and Graves’ disease." (PMID 19412418, 2007). "In type I diabetes mellitus, HLA-A, HLA-B, HLA-C, HLA-DPB1 and GAD1 exhibited significantly different expression levels." (PMID 26062681, 2015). "We also found that compared to type 1 diabetes subjects with classical HLA haplotypes, non-classical HLA subjects had a significantly higher frequency of HLA-B*39:06:02 (p-value=0.01) and HLA-C*07:02:01 (p-value=0.03) alleles, known to be involved in activating the immune response." (PMID 39185409, 2024). "We also identified several COPD-associated genes enriched for immune processes and immune-related diseases (e.g., HLA-C and HLA-DQB1—antigen processing and presentation, HLA-DQB1—type I diabetes mellitus, influenza A, autoimmune thyroid disease)." (PMID 36574990, 2023). "Whereas in our pathway analysis, more genes are identified as part of Type I diabetes mellitus and Allograft rejection pathways (i.e. CD28, HLA-B, HLA-C, HLA-DMB, HLA-DPA1, HLA-DQA2, HLA-DRA, IL12A)." (PMID 22046267, 2011). "This was also reflected in the KEGG pathway analysis of trans-mQTLs where type 1 diabetes was found to be an enriched pathway of relevance in human pancreatic islets, including the following genes: PTPRN2, HLA-DRB1, HLA-B, HLA-C, HSPD1 and HLA-DRB5 (Padj = 6.0×10−4)." (PMID 25375650, 2014).
breast carcinoma (44 papers, 1996 to 2025). "Of the 175 HLA alleles, the association between HLA-C*12:03 and breast cancer risk attained the smallest p-value (OR = 1.29, P = 1.08e-3)." (PMID 35543923, 2022). "For individual cancer sites, we only observed nominally significant associations with breast cancer for homozygosity at HLA-C locus (adjusted OR = 1.38, 95% CI = 1.02–1.87, P = 0.036) and lung cancer for homozygosity at HLA-DQB1 locus (adjusted OR = 1.15, 95% CI = 1.02–1.29, P = 0.022)." (PMID 34421988, 2021). "In addition to the null association between HLA zygosity and non-virus-associated solid tumor overall, we observed a nominally significant association between homozygosity at HLA-C locus and breast cancer and homozygosity at HLA-DQB1 locus and lung cancer." (PMID 34421988, 2021). "KIR 2DL2 in combination with the HLA-C heterozygote ligand (C1/C2) could increase susceptibility to breast cancer." (PMID 27893413, 2016). "Breast cancer tissue was used as a positive control for the specificity of HLA-C staining, since the tumor cells specifically expressed HLA-C." (PMID 40358173, 2025). "After 24-h treatment with IFN-γ, the relative levels of HLA-A, HLA-B and HLA-C mRNA in SKBR3 breast cancer cells were dose dependently increased in all groups treated with different concentrations of IFN-γ compared with the control group with statistical significance (p < .05)." (PMID 40596738, 2025). "We did not observe associations between any HLA allele and breast cancer risk at P < 5e−8; the smallest p value was observed for HLA-C*12:03 (OR = 1.29, P = 1.08e−3)." (PMID 35543923, 2022). "In the context of breast cancer, BAP31 expression showed a positive correlation with TAPBP (r = 0.257, p = 6.55 × 10−18), HLA-A (r = 0.16, p = 9.81 × 10−8), and HLA-C (r = 0.146, p = 1.25 × 10−6)." (PMID 40649753, 2025). "In contrast, we didn’t observe any significant increase in HLA-C mRNA levels and HLA-A mRNA expression levels were unidentifiable in both in vitro models of HER2+ breast cancer." (PMID 36809986, 2023). "Next, we determined whether DVL2 binds to the promoter regions of genes involved in antigen presentation (HLA-A, HLA-C) and T-cell maintenance (STAT1, STAT6, TGFB1) in HER2-positive breast cancer cells." (PMID 36809986, 2023). "The pNK cell cytotoxicity against breast cancer cell lines was related to HLA-C expression rather than NKG2D ligand expression." (PMID 34686187, 2021).